CD4 (CD4 molecule)
Diseases named in the same sentence as CD4 in open-access papers (continued):
Sharing a sentence is not in itself a finding about the gene and the disease.
infection (continued). "Thus, we showed HIF-1 play impairs CD4 T cell activation and differentiation leading to an increase susceptibility to infection with M. tuberculosis and impaired responses to vaccination." (PMID 36064840, 2022). "Low CD4+ T-cell counts, attributable to glucocorticoid and immunosuppressant exposure to a certain extent, are identified as a significant risk factor for higher infection rate." (PMID 36569204, 2022). "Th17 cell and γδ T cells have previously been described in the bladder, but given the increase in Il17 and Il22 transcripts at early time points post infection, even in T cell-deficient mice, we sought to characterize bladder ILC3s, as previous reports had described only CD4+ ILC3." (PMID 35845169, 2022). "Screening may be advisable in high-risk children, particularly those having CD4+ < 100 cells/μL and relevant risk factors, as this group may also present as having asymptomatic infections devoid of diarrhea." (PMID 36355894, 2022). "Additionally, individuals with infection due to human immunodeficiency virus are at greatest risk with low CD4+ T-cell quantitative values, predisposing to risk of severe or fulminant disease." (PMID 36366468, 2022). "Infection of GPX4-deficient mice with Leishmania could lead to a reduction in the number of CD4+ T cells, which contributes to the maintenance of Leishmania in vivo." (PMID 36160441, 2022). "Additionally, infection with Plasmodium causes pro-inflammatory (T helper 1- type) immune response with activation of CD4+, CD4 + 5RO + T cells." (PMID 36504775, 2022). "The decline of CD4+ cell amount and function predisposes inflammation and infection." (PMID 35794311, 2022). "In contrast to previous observation that VHL deficiency enhances effector responses of T cells, mice with VHL-loss in T cells (Vhl cKO) showed a dramatically increased susceptibility to infection with M. tuberculosis by failing to accumulate M. tuberculosis-specific CD4 and CD8 T cells in the lungs." (PMID 36064840, 2022). "The similar levels of single cytokines in both infected groups indicate that pup CD4+ T cells respond same as adult mice to infection, but severity of disease may be associated with lower production of double protective cytokines." (PMID 36131528, 2022). "TLR2 activity could enhance the susceptibility of CD4+ T cells to HIV-1 productive infection, notably by significantly increasing p65 phosphorylation (NF-κB activity marker) in Th17 cells." (PMID 35197986, 2022). "These populations seemed dynamic over the course of infection, with chronic stages associated with a 1.27- and 1.61-fold increase in the abundance of Cd4+ T cells compared to other subclusters (23.64%, 30.21%, and 38.1% in naïve, 25dpi, and 45dpi, respectively), consistent with previous reports." (PMID 36180478, 2022). "Therefore, high levels of CD4 and CD8 are associated with a reduced risk of developing infection.Our experimental data found that lower the levels of iron deposition, the greater the CD4 cell count." (PMID 36324819, 2022). "We also assume all CD4 T cells are equally susceptible to infection, although in reality activated cells may be more susceptible than resting cells." (PMID 35969641, 2022). "Therefore, it is necessary to evaluate additional mechanisms other than CD4+ T cell decline as possible causes for bacterial growth and dissemination, granuloma disruption, and progression of both infections in Mtb-HIV coinfected individuals." (PMID 36405707, 2022). "Pre-existing T-cell immunity, due to past infection (46%) or cross-reactive cellular response (26%), was significantly associated with T-cell response in frequency (CD4+ T-cell, 100% vs 82% after two doses; p = 0.049) and in the magnitude of T-cell response during follow up." (PMID 35529539, 2022).
infection (continued). "However, all vaccinations can be recommended in PLWH, with the exception of live attenuated vaccines which are contraindicated if the CD4+ T cell counts are lower than 200 cells/mm3, as they can potentially cause infection in immunocompromised individuals." (PMID 36552017, 2022). "Moreover, adoptive transfer of wild-type (WT) CD4+GzB+ T cells to Il18ra-/- mice increase survival of this susceptible mouse strain to infection." (PMID 35670567, 2022). "On the other hand, the selective infection of CD4+ cells by HIV leads to the loss of these cells." (PMID 36104731, 2022). "Furthermore, IL-10, IL-12p70 and SDF-1α were found to be significantly associated with lower CD4:CD8 ratios during chronic phase (> 180 days post infection)." (PMID 35165387, 2022). "In addition to baseline CD4+ counts and age implications, CRF01_AE cluster 1 was associated with a poorer probability of achieving IR than infection with cluster 2 (aHR, 1.39; 95%CI, 1.02-1.90) and other subtypes (aHR, 1.83; 95%CI, 1.31-2.56)." (PMID 34895083, 2022). "Depletion of microglia before and during infection augments virus lethality of mice with elevated brain levels of viral loads, infected neurons, neuron loss, CD4 T cells, CD8 T cells, neutrophils, IFN-β, and IFN-γ, showing that microglia exert protective effect." (PMID 34830340, 2021). "Some studies have reported that bortezomib can act on T lymphocytes, lead to a decrease in CD4+ T lymphocytes, and suppress Th17 differentiation in human naive T cells in culture, which could be the reason for the increased risk of infection." (PMID 33527753, 2021). "Th17 are pro-inflammatory CD4+ T cells that are associated with inflammatory immune response in infection or autoimmune disorders, but may also regulate brain architecture and behaviors." (PMID 34641964, 2021). "To investigate the exact cellular mechanisms responsible for schistosome infection-induced bone loss, we analyzed the distribution of RANKL+ CD4+ T cells in mice 8 and 13 weeks after infection, and found that Tfh cells were a major cellular source of RANKL during schistosome infection." (PMID 33735306, 2021). "Furthermore, the mass action term kVT is introduced, which shows the infection caused by the virus V, interacting with uninfected CD4+ T-cells, causing the loss of free virus at the rate −kVT, where k is the rate of infection." (PMID 33806939, 2021). "CD4+ CTLs being highly enriched for the expression of transcripts encoding chemokines involves recruitment of myeloid cells and dendritic cells to the site of viral infection and clears the infection." (PMID 33937545, 2021). "While CD4 counts normalize in the peripheral blood at the end of the acute phase, alterations in CD4+ T cell homeostasis were documented in the gut-associated lymphoid tissue very early upon infection and persist during the chronic phase." (PMID 34456931, 2021). "Since CD4+ T cells also provide help to B cells in lymph node germinal centers, we also assessed levels of polyclonal type 2-associated antibody isotypes in the serum over the course of infection." (PMID 34237106, 2021). "The allele dominance in SARS-CoV-2 cross-reactive CD4+ T cells might be the survival of T cells by competing for affinity with viral peptides and HLA allotypes under infection by viruses with sequence homology." (PMID 35069546, 2021). "Indeed, we and others have reported that the susceptibility of iNKT cell to in vitro infection is higher than that of conventional CD4+ T cells." (PMID 34753817, 2021). "Interestingly, PD-1 knockout (KO) mice develop high numbers of Mtb-specific CD4+ T cells while displaying markedly increased susceptibility to infection; furthermore, PD-L1 KO mice also display enhanced, albeit less severe, susceptibility to infection." (PMID 34946062, 2021).
infection (continued). "In addition, the number of CD4+ intraepithelial lymphocytes (IELs) in BALB/c mice was increased on day 21 post-infection (close to the peak of expulsion), while IELs in susceptible mice (AKR) were mostly CD8+." (PMID 34451389, 2021). "The lower the CD4 count, the more susceptible PLHIVs are to infection and mental stress." (PMID 33632270, 2021). "Reduced CD96−CD226+ cells and elevated CD96+CD226− cells among NK cells especially TIGIT−NK cells, had opposite associations with viral load in the first month of infection, as well as CD4 T-cell counts in including the twelfth month and more than 2 years of chronic infection." (PMID 33717085, 2021). "During PHI, the expression of ICRs has been linked to subsequent CD4 T cell decline and time to viral rebound following treatment interruption – highlighting the clinical relevance of these markers during the early stages of infection." (PMID 34149690, 2021). "These then stimulate more HIV production, loss of additional CD4+ T cells, and more infection." (PMID 34696319, 2021). "The preferential depletion of CD73+ CD4+ T cells in HIV-infection may be due to a combination of susceptibility to infection and a general recruitment of resting memory cells into the CD73-negative CD38+ pool." (PMID 33477692, 2021). "After this point, infected animals were euthanized at 10 weeks after confirmed infection while aviremic, protected animals were longitudinally monitored and euthanized 8 weeks after loss of Leronlimab receptor occupancy (RO) on peripheral blood CD4+ T cells." (PMID 34099693, 2021). "However, because progression of infection is associated with vasculature-associated CD4+ T cells, our data further support parenchymal migratory potential as a key feature of protective CD4+ T cells." (PMID 34554927, 2021). "In-vitro infection of DCs by amastigotes has an important impact on activation and is associated with an overall anti-inflammatory response, associated with poor inflammasome activation, IL-12 production and CD4 T cell proliferation." (PMID 34557194, 2021). "It is likely a combination of the availability of CD4+ target cells and their susceptibility to infection, as well as the availability and functional capacity of SIV-specific CD8+ T cells, that determines viral load, viral load set point, and disease progression." (PMID 34578331, 2021). "The immune response associated with survival against infection by Trypanosoma cruzi, the agent of Chagas disease, infection relies on the generation of a CD4+ T helper 1 (Th1) profile and a strong CD8+ T response that is, however, unable to resolve the infection." (PMID 35071041, 2021). "Indeed, CD4+ T-cell deficient mice that survived the acute infection had significantly elevated viral loads at day 21 PI, demonstrating that these mice eventually fail to control viral replication." (PMID 33572859, 2021). "Here, we defined SARS-CoV-2 S-derived peptides presented with diverse HLA-II alleles on DCs to facilitate analysis of pre-existing, post-infection or vaccine-elicited S-specific CD4+ T(fh) cell responses and their roles in protection, pathogenesis, and prevention of re-infection." (PMID 34004174, 2021). "Importantly, we found that this phenotype was associated with increased lung bacterial burdens, highlighting the association between CD4+ T cells’ defective spatial distribution in the lungs and susceptibility to infection." (PMID 34554927, 2021). "The reduced CD4/CD8 ratio with age also indicates a higher risk of infections." (PMID 34072224, 2021). "Together, these results suggest that the CD4+ T cell pool induced in response to P. vivax infection is heterogeneous and that subpopulations that differ in their helper polarization status associate with the same infection outcome." (PMID 34128836, 2021).
infection (continued). "Resolution of infection between days 14 and 24 was associated with contraction of CD4+ cells in parenchyma and bronchovascular bundles, except along the airway LECs where there appeared to be a stable CD4+ cell niche." (PMID 34611166, 2021). "However, our group and others have recently observed that Tbx21-/- mice maintained IFN-γ producing CD4+ T cells during parasite infection, while remaining highly susceptible to infection." (PMID 33465134, 2021). "Moreover, the effective analogs showed co-receptor independent inhibition, as they inhibited CXCR4-, CCR5- and dual tropic virus variants and even the infection of CD4- cells." (PMID 34073578, 2021). "Infection with C. rodentium is associated with IL-23 dependent CD4+ LTi cell responses." (PMID 34804991, 2021). "These individuals experience a slower loss of CD4+ T cells early in infection." (PMID 35126374, 2021). "Previous studies have found that the rate of postoperative infection in orthopedic joint surgeries among HIV-positive patients was 23%, and CD4-CC < 300 cells/μl, hospitalization, multiple traumas, and low plasma albumin levels were all found to be associated with postoperative infections." (PMID 34616598, 2021). "Also, as observed in adults, KIR3DL1-HLA-Bw4 has been associated with lower plasma viral load and higher CD4+ T-cell counts in all ages in paediatric infection." (PMID 34793581, 2021). "Taken together, these observations suggest that intragenic methylation could be a late event during infection as well as intragenic methylation was positively associated with CD4+ counts and viral loads." (PMID 34925380, 2021). "CB2 agonist have been shown to decrease CXCR4-activation-mediated G-protein activity and MAPK phosphorylation, alter the cytoskeletal architecture of resting CD4+ T and impair productive infection following cell-free or cell-associated viral acquisition of CXCR4-tropic HIV-1 in resting cells." (PMID 32471272, 2020). "CD4 cells play a major role in the immune response to gastrointestinal pathogens, and it has been shown that low CD4 counts are associated with increased risk of infection with enteric parasites and chronic diarrhea." (PMID 32351207, 2020). "Binding antibodies to the V1/V2 region of the envelope protein, IgG3 subclass V1/V2-specific antibodies, polyfunctional Env-specific CD4 T cells, low mucosal Env-specific IgA, and antibody-effector activities all show evidence of being associated with reduced risk of infection." (PMID 32881968, 2020). "Thus, changes in composition and function of naive and memory CD4 T cells can result in impaired immunity and increased susceptibility to subsequent infections." (PMID 32903436, 2020). "This pattern could emerge if CD4-independent variants are only favored in highly pathogenic NHP infections with severe immunodeficiency." (PMID 32992787, 2020). "The virus primarily infects CD4+ T-cells and causes lifelong infections in humans." (PMID 33414779, 2020). "Furthermore, loss of peripheral and colonic CD161+ CD4+ T cells in untreated infection was associated with levels of viral load." (PMID 33322496, 2020). "Decline of CD4 T cells following infection is also associated with fatal EVD in humans." (PMID 32992829, 2020). "Conversely, T-bet expression could be related to a favorable clinical outcome, since it was associated with greater CD4 + T cell counts and nadir value and with the development of a lung-restricted TB instead of a disseminated infection." (PMID 31906962, 2020). "In addition, lack of thymic output prior to persistent S. Typhimurium infection results in a loss of control over infection, despite the fact that Salmonella specific CD4+ T cells are elevated." (PMID 33604308, 2020). "In addition, IL-22 deficient mice (Il22−/−) succumbed to infection, which correlated with reductions in the numbers of CD4+ IFN-γ+ T cells, reduced IFN-γ levels, and diminished nitric oxide synthase type 2 (NOS2) expression in the lungs." (PMID 32517114, 2020).
infection (continued). "An investigation of whether infection with multiple founder variants resulted in different disease outcome using CD4+ T cell count and viral load measurements as measures of disease outcome was done." (PMID 32886726, 2020). "Studies of the mechanisms underlying CD4+ T cells roles in S. aureus infection indicate that IFNγ may be dispensable during primary infection, whereas the requirement for IL-17 varies depending on the infection model." (PMID 33291260, 2020). "Thus, the infection was associated with the differentiation of splenic CD4 T cells, which became more sensitive to FasL-mediated cell death." (PMID 33604562, 2020). "The risk of infection after GCS therapy is associated with a decrease in blood CD4+ T cell count." (PMID 32893490, 2020). "In human ANDV infection, little is known about CD4+ Treg cells, which may be involved in control immunopathology associated to the infection." (PMID 32984065, 2020). "Finally, we identify perturbations in the CD4+ T cell and B cell compartments that are associated with multivariant infection." (PMID 32886726, 2020). "Consequently, the number of splenic Ag-experienced (Ag-exp) CD11a+CD49d+ CD4+ T cells, which contain parasite-specific CD4+ T cell populations, was significantly attenuated in mice with a CD4 T cell–specific mTOR deficiency on days 5 and 15 of infection." (PMID 32817333, 2020). "Natural infection was associated with a significant increase in CD4+ T-cell responses." (PMID 32572168, 2020). "Considering the lack of enough sample size and study design, whether there is a discrepancy of T lymphocyte subgroups dominance in different periods of infection should be explored further, but the CD4+ T lymphocyte counts have been linked to disease severity." (PMID 32196410, 2020). "Additionally, we observed an infection-induced increase in polyfunctional CD4+ T cells in the resistant SV/129 model, opposing an infection-induced increase in CD4+IL-10+ cells in susceptible BALB/c mice." (PMID 30881923, 2019). "Interestingly, depletion of NK cells in E. muris-primed mice decreased the numbers of memory CD4 T cells and antibody-producing B cells, and made animals more susceptible to infection after re-challenge with IOE." (PMID 31134081, 2019). "Genotyping of these polymorphisms could be used to estimate the risk of poor CD4 restoration, mainly in patients who are diagnosed late in the course of infection." (PMID 30921390, 2019). "Prior infection with mildly pathogenic strains provided protection against subsequent highly virulent pneumococcal infection through the formation of IL-17 producing CD4+ Trms." (PMID 31130965, 2019). "Further analysis of the association between CD4+ T cell response profiles and susceptibility to infection may lead to a better understanding of protective immune response, and to the optimal antigen selection." (PMID 31149870, 2019). "In adults, the reduced T-cell receptor repertoire due to loss of CD4 T cells during untreated infection may remain truncated if the increase in CD4 count mainly stems from residual cell proliferation and survival." (PMID 30624717, 2019). "Altogether the CXCR6 characteristics and, though at a lesser level, the Trim5α ones, might contribute to modify the susceptibility to infection of the various memory CD4 T-cell compartments to HIV-2 compared to HIV-1." (PMID 31095640, 2019). "Furthermore, subtype D infection was associated with the greatest CD4 cell decline in a cohort of women in Sub-Saharan Africa who were either subtype A, C, or D." (PMID 31795223, 2019). "The presence of activated CD4+ T cells in submucosa increases the probability of infection, where the predominant microbiota could be implicated through the modulation of an inflammatory microenvironment." (PMID 30787929, 2019).